S100B (S100 calcium binding protein B)
Diseases named in the same sentence as S100B in open-access papers (continued):
Sharing a sentence is not in itself a finding about the gene and the disease.
delirium (continued). "Patients who developed delirium had higher serum S100B levels during the first three days in the ICU than those who did not (p = 0.01)." (PMID 30086136, 2018). "This study confirmed that serum galectin‐3 levels were significantly elevated in postpartum ICU women, especially in delirium women, and moreover, its serum levels were correlated with serum S100B and C‐reactive protein levels as well as APCHCE II scores." (PMID 28828226, 2017). "The current study also demonstrated that serum S100B and C‐reactive protein levels were the independent predictors for delirium among postpartum women in ICU." (PMID 28828226, 2017). "Comatose patients had higher S100B levels than delirium patients (median (interquartile): 0.14 (0.11, 0.48) versus 0.1 (0.05, 0.37) μg/L, P = 0.007)." (PMID 24883321, 2014). "Levels of brain-specific proteins were comparable between the groups, except for a borderline-significant elevated level of S100-β in the delirium group (P = 0.07)." (PMID 22206727, 2011). "Future studies are needed to elucidate the place of S100B in the pathophysiological pathway leading to delirium (and possibly dementia) and investigate its role as biomarker for delirium." (PMID 19473521, 2009). "More studies are needed to elucidate the role of S100B proteins in the pathophysiological pathway leading to delirium and to investigate its possibility as biomarker for delirium." (PMID 19473521, 2009). "With regard to S-100β, our data are consistent with those from patients with delirium after cardiac surgery." (PMID 18457586, 2008). "The study did not include other relevant biomarkers of systemic or neuroinflammation (e.g., interleukin-6, TNF-α, or S100B protein), which could have provided a broader mechanistic understanding of the inflammatory contribution to delirium." (PMID 41303282, 2025). "Elevated S100B levels, along with neurofilament light chains (NfL), have been identified as key indicators for predicting delirium and unfavorable outcomes in patients suffering from septic encephalopathy, underscoring their potential as specific and prognostic biomarkers for this condition." (PMID 39201697, 2024). "Additionally, patients with delirium had higher plasma IL-6 concentrations, and there was a positive correlation between S100B and IL-6 levels." (PMID 39201697, 2024). "The expression of S100β increased in POD patients, which reduced the function of the blood-brain barrier, aggravated the neuroinflammatory response, and eventually caused delirium." (PMID 38779218, 2024). "Interestingly, van Munster also studied the role of S100B in predicting delirium, and demonstrated that among patients undergoing surgery, S100B levels were higher in those who developed delirium than in patients who did not29." (PMID 36973363, 2023). "We hypothesized that increased levels of S100B, NSE and Tau would be associated with an increased risk of delirium." (PMID 36973363, 2023). "Our systematic review identified 12 studies that investigated S100β serum concentration as a predictor for delirium during hospitalization, eight of which controlled for illness, and six out of these eight controlled for cognitive impairment before hospitalization." (PMID 37360340, 2023). "The authors reported that S100B levels remain high after delirium, which could indicate an active stimulation of astrocytes or an increase of BBB’s permeability." (PMID 36973363, 2023). "Moreover, concomitant elevation of S100B in the serum and in the cerebrospinal fluid (when measured) in patients who developed delirium argue against an extracerebral source of this biomarker." (PMID 30086136, 2018). "Higher levels of S-100B were associated with a longer duration of delirium, but no comparison with non-delirious patients was made." (PMID 29801516, 2018). "BBB disruption and neuron injury via neuroinflammation may contribute to delirium, and therefore, S100B provides support for this theory." (PMID 27119013, 2016).
delirium (continued). "The simultaneous comparison of cortisol, IL-6, IL-8, and S100B protein revealed that the highest levels of cortisol and IL-8 were observed before delirium but the highest levels of IL-6 and S100B were observed during delirium." (PMID 26417595, 2015). "We could not reproduce the findings from previous studies that reported protein pattern specific for delirium in serum, including haemoglobin-β, S100-β or other unidentified peaks at m/z 5030 and 5179 in rats withdrawn from cocaine exposure." (PMID 21426560, 2011). "The aim of this study was to compare the level of S100B and NSE of patients before, during and after delirium with patients without delirium and investigate the possible associations with different subtypes of delirium." (PMID 19473521, 2009). "Possibly, the high frequency of dementia after delirium could also be predicted by the level of S100B during delirium." (PMID 19473521, 2009). "Moreover, a subgroup analysis identified that surgical patients who developed delirium during hospitalization had a mean difference in S100β serum concentration at hospital admission of 0.04 ng/ml greater than surgical patients who did not develop delirium during hospitalization." (PMID 37360340, 2023). "This means that S100B may not raise in all delirium patients and further research should explore the association between S100B, NSE, Tau and subsequent cognitive decline." (PMID 36973363, 2023). "Thus, higher postoperative serum biomarkers like S100β or IL-6 could represent a mirror of the inflammatory processes in the CNS during delirium." (PMID 37373482, 2023). "The absence of an association between sTNRF1, Protein C, and S100B and ED delirium duration may have been a type 2 error (false negative)." (PMID 31856187, 2019). "Interestingly, we found that, compared to serum S100B levels, serum galectin‐3 levels possessed the similar predictive ability for delirium based on AUC; notably, its predictive ability significantly exceeded those of serum C‐reactive protein levels and APCHCE II scores." (PMID 28828226, 2017). "Postoperative delirium and cognitive dysfunction may have common contributing factors and biomarkers such as apolipoprotein E isoforms, cortisol signaling, pro-inflammatory cytokines, neurodegenerative marker S100B, copeptin and 6-sulfatoxymelatonin levels." (PMID 26106326, 2015). "We have summarized the 13 most studied proteins (IL-6, CRP, IL-8, S100B, IL-10, TNF-a, IL-1b, Cortisol, MCP-1, GFAP, IGF-1, IL-1ra and NFL) about delirium." (PMID 39700095, 2024). "Markers of neuronal damage, such as S100B and NfL (related to disturbances in astrocytic integrity), have been associated with delirium, but these markers of brain injury could be associated with established, and not necessarily incident, delirium." (PMID 37251808, 2023). "Plasma S100B, NSE and Tau were measured before and during delirium in 21 patients with delirium during hospital stay (delirium incidence)." (PMID 36973363, 2023). "Since biological half-lives in serum NSE and S100β were shorter (approximately 48 h) than that of pNF-H (approximately 96h), more critical time window would be required to diagnose of and evaluate of the severity of delirium by NSE and S100β than pNF-H." (PMID 31574089, 2019). "Compared with Group C, S100β and GFAP decreased and incidence of postoperative delirium reduced at T3–4 in Group N, the difference was statistically significant (P<.05)." (PMID 28489775, 2017). "Galectin‐3, C‐reactive protein, and S100B levels and APCHCE II scores were identified as independent predictors for delirium." (PMID 28828226, 2017). "Consistent with this statement, we also found that serum S100B and C‐reactive protein levels were obviously elevated in postpartum ICU women, especially in delirium women." (PMID 28828226, 2017).
delirium (continued). "In the current study, besides serum S100B and C‐reactive protein levels in addition to APCHCE II scores, galectin‐3 in serum was demonstrated to be an independent predictor for delirium of postpartum women in ICU." (PMID 28828226, 2017). "Serum and CSF S100B protein levels were raised in patients with NPSLE, especially among patients with organic brain syndrome, seizures, cerebral vascular accident and psychosis." (PMID 22420334, 2012). "Serum biomarkers such as S100β and neurofilament light chain show potential for illuminating the pathophysiology of ICU delirium, particularly astrocytic and axonal injury, but current evidence is limited by methodological inconsistencies and a lack of replication." (PMID 40889075, 2025). "In obstetric patients, the rise in S100B levels was approximately three times greater in those who developed delirium than in those who did not." (PMID 38928583, 2024). "It is worth mentioning that they did not assess the role of S100B in delirium occurrence and measurements S100B occurred 48 h after admission." (PMID 36973363, 2023). "In the current research, pre-infusion of HS reduced the levels of IL-6, TNF-α and S100β compared with normal saline group, which is in accordance with prior studies that found higher levels of S100β in patients with delirium than in patients without delirium." (PMID 38082215, 2023). "In the process of neuroinflammation, biomarker S100B may play a role as a validated measure of BBB disruption and contribute to delirium." (PMID 32987655, 2020). "Interestingly, putative delirium biomarkers such as NSE and S-100β were reported/found to be irrelevant." (PMID 31263968, 2019). "Therefore, serum S100B and C‐reactive protein levels and APCHCE II scores have the potential to be the good predictors for delirium among postpartum ICU women." (PMID 28828226, 2017). "It is also consistent with the previous study, in which higher S100β levels were found in patients with delirium than in patients without delirium." (PMID 29137628, 2017). "Elevated CSF levels of S100B, a marker of CNS damage derived largely from astrocytes, were reported in active delirium in patients with hip fracture compared with those without delirium." (PMID 24067500, 2013). "The S100B protein is an indicator of glial activation and/or death; thus, it is a nonspecific marker of brain injury The S100B protein has been shown to be elevated in patients with delirium." (PMID 23270646, 2012). "Previously, it was demonstrated that delirium is associated with elevated levels of IL-6, IL-8, and S100-β in non-ICU patients and with IL-6 and S100-β in ICU patients with sepsis." (PMID 22206727, 2011). "The correlation between the levels of S100B and the proinflammatory cytokines IL6 and IL8 in the patients in this study can be seen as an indication that the neuroinflammatory system is related to possible cerebral damage due to delirium." (PMID 19473521, 2009). "In our study of elderly patients admitted for acute surgical repair of hip fracture we found higher S100B levels in patients with delirium than in patients without delirium with the highest levels of S100B during delirium." (PMID 19473521, 2009). "We are not aware of studies that determined NSE and S100B in both CSF and blood among patients with cognitive deficits such as delirium." (PMID 19473521, 2009). "Comparing the first samples during delirium to samples of non-delirious patients, a difference was observed in S100B (median 0.16 versus 0.10 μg/L, p = < 0.001), but not in NSE (median 11.7 versus 11.7 ng/L, p = 0.97)." (PMID 19473521, 2009). "S100B levels 'before' and 'after' delirium were still higher than those from 'non-delirious' patients." (PMID 19473521, 2009).
delirium (continued). "In the context of sepsis-associated encephalopathy (SAE), which frequently affects older individuals and primarily presents as delirium without focal neurological symptoms, the S100B protein emerges as a promising biomarker for quantifying neuronal and axonal injury." (PMID 39201697, 2024). "Levels S100B on admission did not predict delirium in acutely ill elderly patients." (PMID 36973363, 2023). "In line with this, low levels of S100b rule out delirium, although in an off-pump CABG setting." (PMID 30367354, 2018). "Brain dysfunction including coma and delirium was evaluated by the Glasgow Coma Score (GCS) or the Richmond Agitation Sedation Scale (RASS) combined with the Confusion Assessment Method in the ICU (CAM-ICU) and with the measurement of serum biomarker of brain injury S100B protein." (PMID 24883321, 2014). "However, S100B levels on admission did not predict delirium in affected elderly patients." (PMID 38928583, 2024). "The authors observed a difference between the levels of S100B, but not NSE, in the first samples taken during delirium and the samples from nondelirious patients." (PMID 26417595, 2015). "S100B (μg/L) and NSE (ng/mL) values during delirium versus no delirium." (PMID 19473521, 2009).
injury (69 papers, 2009 to 2025). Damage inflicted on the body as the direct or indirect result of an external force, with or without disruption of structural continuity. "In this study, multiplex and singleplex electrochemiluminescence immunoassays (ECLIA) were utilized to examine the release kinetics of four protein biomarkers, namely, h-FABP, GFAP, S100β, and Tau, associated with mild traumatic brain injury." (PMID 37397462, 2023). "These elevated S100B levels occur because brain trauma causes astrocytes to release S100B into their surrounding environment." (PMID 36618764, 2022). "Therefore, serum levels of Netrin-1, NSE, and S100β are closely associated with the severity of brain injury in SAE and serve as effective predictors of short-term mortality, enhancing prognostic accuracy in clinical practice." (PMID 40714984, 2025). "S100b has long been acknowledged as a sensitive biomarker for assessing brain damage and blood–brain barrier integrity, currently employed for risk stratification in mild brain injury." (PMID 38541055, 2024). "In patients with moderate or severe brain injury, S100B concentrations continue to increase, reaching an upper limit at 24 h after cardiopulmonary bypass." (PMID 39910669, 2025). "It should be noted that the use of S100B levels in biological fluids in order to monitor the effects of acute brain injury, also in light of official guidelines for this purpose, constitutes a topic that has been especially addressed in recent years." (PMID 37298554, 2023). "S100B is an astrocyte specific marker of brain damage and increases rapidly in both blood and CSF upon events like traumatic brain injury and infectious diseases." (PMID 36670437, 2023). "Cerebrospinal S100B can be valuable as an indicator of consequence in adults with serious brain injury." (PMID 36140268, 2022). "In case of brain injury, S-100B not only leaks out from damaged glial cells but is also actively secreted as a part of the proinflammatory-axis." (PMID 36597568, 2022). "Serum S100B protein represented the seriousness of the injury and aided in the prediction of outcomes after a serious brain injury." (PMID 36140268, 2022). "The secondary aims were to establish temporal profile of urine S100B over 48 h after trauma of patients with intracranial hemorrhage due to head trauma and to study how renal function and the chemical properties of urine affect urine S100B." (PMID 31388712, 2021). "It is becoming increasingly clear that temporal changes of S100B in serum are highly dynamic following brain injury." (PMID 28717351, 2017). "S100B spikes up after hemorrhagic shock and correlates with shock severity which decreases it's value as a single biomarker for traumatic brain injury." (PMID 27468268, 2016). "Raised S100-B has value in predicting adverse neurological outcomes in cardiac arrest and traumatic brain injury." (PMID 25849778, 2015). "Here it is of interest to note that intracerebroventricular and even intraperitoneal application of S100B increases progenitor cell proliferation as well as neuronal differentiation and survival of newborn cells in mice after brain injury." (PMID 26364276, 2015). "S100B has been recently recognized as a DAMP released by astrocytes after acute or chronic brain injury, and it is a known RAGE ligand." (PMID 25265561, 2014). "Opposite to common reasoning, we found the passage of S100B from CSF to serum impaired following acute brain injury." (PMID 20671945, 2010). "Opposite to common reasoning, in our study the passage of S100B from CSF to serum was impaired following acute brain injury." (PMID 20671945, 2010). "If validated in larger studies, urinary S100B could transform how IH-related brain injury is detected and monitored." (PMID 40963746, 2025). "S100-β is a calcium-binding protein primarily secreted by glial cellsand plays a significant role in the pathophysiological processes followingtraumatic brain injury." (PMID 39801405, 2025).